TLR8 (toll like receptor 8)
Diseases named in the same sentence as TLR8 in open-access papers (continued):
Sharing a sentence is not in itself a finding about the gene and the disease.
influenza (16 papers, 2014 to 2025). An acute viral infection of the respiratory tract, occurring in isolated cases, in epidemics, or in pandemics; it is caused by serologically different strains of viruses (influenzaviruses) designated A, B, and C, has a 3-day incubation period, and usually lasts for 3 to 10 days. "TLR7 and TLR8 have been recently identified as important sensors of ssRNA from the viral genomes of influenza, vesicular stomatitis virus, and the human and simian immunodeficiency viruses, HIV and SIV28." (PMID 28128342, 2017). "TLR7 and TLR8 are related phylogenetically and functionally and have been identified as important sensors of ssRNA from the viral genomes of influenza and vesicular stomatitis virus as well as HIV itself." (PMID 26154133, 2015). "A TLR8 biased adjuvant therefore, such as UM-3005, may be particularly efficacious at increasing infant responses to influenza." (PMID 32210973, 2020). "Moreover, in influenza infection, viral entry, uncoating, and endosomal acidification were required for cytokine induction by human neutrophils via TLR8 and TLR7 signaling." (PMID 33003471, 2020). "TLR3, TLR7, TLR8, and RIG-I are known to be involved in sensing influenza viral Ags and activating downstream signaling pathways." (PMID 38112660, 2023). "Changes in expression of different toll-like receptors (TLRs) (TLR2, TLR3, TLR4, TLR7, TLR8, and TLR9) have been reported before in human monocytes and dendritic cells from seasonal influenza infected patients." (PMID 30682165, 2019). "Though studies have shown TLR8 is activated during influenza and RSV infections, there is no current knockout (KO) mouse model available to differentially observe TLR8’s role during these infections." (PMID 37662905, 2023). "TLRs, such as TLR3, TLR7, and TLR8, are membrane-bound PRRs that recognize viral RNA: TLR3 detects double-stranded RNA (dsRNA), a byproduct of influenza replication, TLR7/8 sense single-stranded RNA (ssRNA) from the viral genome, while TLR2 and TLR4 recognize influenza-induced DAMPs." (PMID 40692679, 2025).
Obesity (14 papers, 2015 to 2026). Accumulation of substantial excess body fat. "Given that RSV is sensed by myeloid cells via TLR4/TLR8 pathways, we asked if maternal obesity compromises fetal myeloid cell responses to ex vivo RSV infection." (PMID 36645353, 2023). "This suggests that during obesity, TLR8 must be present to initiate the activation of the immune system, responsible for AT expansion." (PMID 36432612, 2022). "The increased AT levels of TLR8 in obesity and T2DM were confirmed to be positively correlated with inflammatory markers like C-reactive protein and the expressions of inflammatory cytokines and chemokines." (PMID 32684073, 2020). "Next, we found that the increased TLR8 gene expression in the adipose tissues in obesity/T2D paralleled with enhanced expression of monocyte/macrophage markers such as CD68, CD11c, CD86, and CD163." (PMID 27980459, 2016). "Taken together, the present data show significantly elevated TLR8 mRNA and protein expression in the adipose tissue in obesity/T2D." (PMID 27980459, 2016). "The hub genes calculated by Cytoscape software are MNDA (score 320), CYBB (score 314), CD86 (score 312), FCGR2C (score 242), NCF2 (score 240), LCP2 (score 182), TLR8 (score 148), HLA-DRA (score 54), LCP1 (score 30), and PTPN22 (score 8), which are considered to be associated with obesity-related AF." (PMID 36671813, 2023). "There is little information about TLR8 in obesity-mediated inflammation." (PMID 31582899, 2019). "The elevated levels of TLR8 in obesity/T2DM are consistent with the increase of inflammatory mediators and may represent an immune marker of metabolic inflammation." (PMID 31582899, 2019). "We further asked whether the TLR8 protein expression was also elevated in the adipose tissue in obesity." (PMID 27980459, 2016). "Human TLR8 is a part of the nucleic acid-sensing TLRs that recognize viral ss/ds RNAs and bacterial RNA; however, TLR8 agonist(s) associated with obesity/T2D are still not known." (PMID 27980459, 2016). "The elevated adipose tissue expression of TLR8 in obesity/T2D has consensus with inflammatory signatures and may thus represent an immune marker of metabolic inflammation." (PMID 27980459, 2016). "Whereas the changes in TLR2/TLR4 expression in the adipose tissue are regarded as important actors in metabolic inflammation, the changes in the adipose tissue expression of endocytic TLR8 in obesity/T2D remain unclear." (PMID 27980459, 2016). "Notably, the changes in the adipose tissue expression of TLR8 in obesity/T2D are not well understood." (PMID 27980459, 2016). "These authors propose a model in which pro-inflammatory monocytes in individuals with obesity respond to circulating factors via Toll-like receptors (TLR4 and TLR8)." (PMID 39861442, 2025). "We applied the Attie Lab Diabetes database to verify the hub gene mRNA levels in obesity, which indicated that expression of TYROBP, TLR8, FCER1 G, HCK, NCF2, CTSS and C3AR1 was significantly up-regulated in 10-week obese mice as compared to the lean group." (PMID 32684073, 2020). "Our data show strong positive correlations between adipose IRF5 gene expression and that of TLR2, TLR7, TLR8, TLR9, MyD88, IRAK-1, and IRF3 in obesity." (PMID 31718015, 2019). "The magnitudes of the obesity-induced upregulation of the TLR1, TLR4, TLR5, TLR8, TLR9, and TLR12 genes in the visceral adipose tissue were even greater in the diet-induced obesity (DIO) mice than in the ob/ob mice." (PMID 26681840, 2015). "Regarding expression of TLRs, their downstream signaling mediators and IRFs, adipose expression of TLR2 (p = 0.018), TLR3 (p = 0.010), TLR8 (p = 0.048), IRAK1 (p = 0.047), and IRF5 (p = 0.016) was significantly higher in participants with obesity compared to NW participants." (PMID 36552771, 2022).
Obesity (continued). "Regarding the adipose tissue changes in TLR8 expression in obesity/T2D, our data show that in non-diabetic obese individuals, the upregulated TLR8 mRNA expression correlated with corpulence-related phenotypes including BMI and body fat percentage." (PMID 27980459, 2016). "Our data also show elevated TLR8 protein expression in the adipose tissue in obesity with/without T2D and, notably, a good agreement (r = 0.86, P < 0.0001) was found between gene and protein expression of TLR8." (PMID 27980459, 2016). "Multiple TLRs, including TLR2, TLR3, TLR4, TLR5, TLR8, TLR9, and TLR10, have been indicated in the regulation of PAMPs from gut microbiota and DAMPs from metabolic stress and tissue damage, which initiate the inflammatory responses contributing to the development of obesity-related chronic diseases." (PMID 31582899, 2019).
HIV-1 infection (13 papers, 2013 to 2025). The type species of lentivirus and the etiologic agent of acquired immunodeficiency syndrome (AIDS). "Another study assessed TLR7 and eight gene polymorphisms associated with susceptibility to HIV-1 infection and found that TLR8 polymorphisms could affect HIV-1 infection." (PMID 37298575, 2023). "Increased expression of TLR6, TLR7, and TLR8 mRNA has been observed in chronic untreated HIV-1 infections." (PMID 37298575, 2023). "Therefore, we assumed that these genes may play an important role in HIV-1 infection, and examined TLR8 first to validate our hypothesis." (PMID 37134013, 2023). "This suggests that combining SMACm with the TLR8 agonist may be effective for in vivo reservoir elimination by reducing the viral reservoir as well as inducing antiviral adaptive immunity to control HIV-1 infection over time, thereby further decreasing the HIV-1 reservoir." (PMID 40141220, 2025). "How prior HIV-1 infection status and timing of ART initiation relate to monocyte pattern-recognition receptor crosstalk between TLR8 and RLRs remains uncertain." (PMID 41206241, 2025). "As an example, agonists for TLR3, TLR7, TLR8, and TLR9 have been shown to be capable of inhibiting HIV-1 infection and induced IFN-α-stimulated gene expression in PBMCs in vitro." (PMID 38994942, 2024). "When TLR3, TLR7, TLR8, and TLR9 agonists were added before HIV-1 infection, they significantly reduced peripheral blood mononuclear cell infection." (PMID 35211115, 2022). "Prior addition of TLR3, TLR7, TLR8, and TLR9 agonists was shown to inhibit HIV-1 infection in peripheral blood mononuclear cells (PBMCs); TLR8 and TLR9 agonists were found to be more effective in blocking HIV-1 replication, along with the activation of other antiviral sensors." (PMID 37298575, 2023). "Interestingly, the addition of TLR8 and TLR9 agonists 48 h and 72 h after HIV-1 infection, respectively, were highly effective in preventing HIV replication." (PMID 35211115, 2022). "In macrophages, the interaction of toll-like receptor 8 (TLR8) and HIV-1 induces autophagy by Beclin 1-dependent dephosphorylation of transcription factor EB (TFEB) and subsequently its nuclear translocation during the initial stages of HIV-1 infection." (PMID 33669846, 2021). "Interestingly, the percentage of TNF-α -producing monocytes following TLR8 stimulation strongly positively correlated with HIV-1 RNA levels both in acute and chronic HIV-1 infection." (PMID 23818854, 2013). "Thus, we assessed inflammasome activation by HIV-1 infection or VbP treatment with and without pretreating THP-1 cells with agonists of TLR1/2 (Pam3CSK4), TLR7/8 (CL075), TLR8 (TL8-506), or TLR4 (LPS)." (PMID 37417868, 2023).
rheumatoid arthritis (13 papers, 2015 to 2025). A chronic, systemic autoimmune disorder characterized by inflammation in the synovial membranes and articular surfaces. "Studies show that there are high levels of crosstalk between TLR2 and TLR8, which can stimulate the secretion of inflammatory cytokines related to rheumatoid arthritis and other inflammatory diseases." (PMID 35042504, 2022). "MiRs, being small ssRNA strands, have recently been documented as serving as ligands for TLR7 and TLR8, propagating such diseases as Alzheimer's disease, rheumatoid arthritis, and aGVHD." (PMID 30455702, 2018). "Human TLR-8 got activated by the endogenous ligands might lead to the onset of many inflammatory diseases such as rheumatoid arthritis RA as well as OA." (PMID 36262248, 2022). "Likewise, for rheumatoid arthritis (RA), our work makes a plausible link between exRNA in synovial fluid contributing to joint inflammation, the emerging role of NETs in RA and even a hitherto enigmatic but therapeutically relevant role of TLR8." (PMID 38783164, 2024). "It is investigated that the anti-inflammatory properties of mianserin, a serotonin (5HT) receptor antagonist, was able to inhibit the endosomal TLR8 in primary human cells and inhibited the spontaneous release of TNF and IL-6 from rheumatoid arthritis synovial membrane cultures." (PMID 39234104, 2024). "Additionally, as shown in this study, N-glycans are selective inhibitors of TLR-8 activation whereas CQN is not and this treat is considered a challenge in the therapy of rheumatoid arthritis with antimalarials." (PMID 32477333, 2020).
pulmonary tuberculosis (11 papers, 2008 to 2024). A bacterial infection that affects the lungs and is caused by Mycobacterium tuberculosis. "In the unadjusted recessive model, carriers of the TLR8 rs3764880 A/A (OR = 1.90, 95% CI: 1.00–3.59, p = 0.04, G/G-A/G vs. A/A) genotype were associated with a higher risk of developing pulmonary TB." (PMID 38398882, 2024). "In the unadjusted dominant model, TLR8 rs3764880 A allele was associated with a higher risk of developing pulmonary TB (OR = 1.41, 95% CI: 1.09–1.83, p = 0.001, GG vs. G/A-A/A)." (PMID 38398882, 2024). "Here we describe a genetic association study aiming to identify polymorphisms withinthe TLR pathway which confer increased susceptibility to adult pulmonary TB and forthe first time report evidence implicating TLR8." (PMID 18927625, 2008). "We found evidence that TLR8 polymorphisms are associated withsusceptibility to pulmonary TB among males." (PMID 18927625, 2008). "The G allele of rs3764880, which abolishes a putative start codon within the alternative TLR8 transcript isoform a, conferred a protective effect on susceptibility to pulmonary tuberculosis in Indonesian and Russian men, as well as on HIV disease progression in Germans." (PMID 23468661, 2013). "Despite the fact that the quality of these studies varies greatly, genetic variation in an increasing number of genes (e.g., NRAMP1, HLA class II, VDR, MAL/TIRAP, DC-SIGN, MCP-1, TLR8) has been found to be associated with complex susceptibility to pulmonary TB." (PMID 20027210, 2009). "A recent association study screening variation at 18 genes involved in the Toll-like receptor (TLR) pathway identified four polymorphisms in the TLR8 gene, which is located on chromosome X (Xp22), which seemed to be associated with complex susceptibility to pulmonary TB in an Indonesian cohort." (PMID 20027210, 2009). "In this study, we tried to find the association of polymorphisms of TLR2, TLR8, and four polymorphisms of the VDR gene (FokI, TaqI, ApaI, and BsmI) with pulmonary TB progression in the Kazakh population." (PMID 38398882, 2024). "Taken together, our results provide evidence,for the first time, of a role for the TLR8 gene insusceptibility to pulmonary TB across different populations." (PMID 18927625, 2008). "A/A polymorphism of TLR8 (rs3764880) and T/T polymorphism (BsmI, rs1544410) of VDR genes may act as biomarkers for pulmonary tuberculosis in the Kazakh population." (PMID 38398882, 2024). "Such BCG-induced IL-12 pathway activation is mediated via sensing of viability by TLR8 whose functional alleles correlate with protection vs. pulmonary TB in BCG-immunized adults, and is not observed with killed vaccines." (PMID 34326836, 2021). "The objectives of this study were to determine whether TLR8 and TLR9 SNPs were associated with the development of latent TB infection (LTBI) and the subsequent pulmonary TB (PTB) in a Chinese Han population." (PMID 30424735, 2018). "Therefore, it may be implicated that the M.tuberculosis sRNA_1096 may bind to TLR8 in a similar way asmiR-21 does through its GUUG motif and thus may activateimmune and inflammatory responses and explains a role of TLR8in pulmonary tuberculosis." (PMID 30237679, 2018). "Supporting this model is the association of a single-nucleotide polymorphism in TLR8 (TLR8 A1G; rs3764880) which confers a significant protective effect against HIV disease progression; however, this same polymorphism increases male susceptibility to pulmonary tuberculosis." (PMID 23166493, 2012). "However, theprecise mechanism of TLR8 in pulmonary tuberculosis is not yetknown." (PMID 30237679, 2018).
chronic hepatitis B (10 papers, 2020 to 2024). "Chronic hepatitis B (CHB) is associated with a dysfunction of the immune response implicating toll-like receptor 8 (TLR8)." (PMID 35337149, 2022). "Immunotargets including checkpoint inhibitors and toll-like receptor 8 agonists have recently gained attention for the recovery of hepatitis B virus (HBV)-specific T cell exhaustion in chronic hepatitis B(CHB)." (PMID 37081509, 2023). "(NCT03615066, NCT03491553), and DN1508052–01 (NCT03934359) are TLR8 agonists in clinical trials with different clinical implications, including various cancers and chronic hepatitis B." (PMID 36476317, 2022). "The TLR8 agonist GS-9688 (selgantolimod) was discovered as a potent and selective oral TLR8 agonist for the treatment of chronic hepatitis B. In a preclinical study, a reduction in viral markers was observed in HBV-infected primary human hepatocytes treated with GS-9688." (PMID 36476317, 2022). "In this context, the toll-like receptor 8 (TLR8) agonist selgantolimod (SLGN) has been investigated in preclinical models and clinical trials for chronic hepatitis B (CHB)." (PMID 38697771, 2024). "Compared with healthy controls, TLR8 expression and IFN-γ, TNF-α, and IL-12 induction were reduced in PBMCs from chronic hepatitis B (CHB) patients." (PMID 36476317, 2022).
melanoma (10 papers, 2014 to 2024). A malignant, usually aggressive tumor composed of atypical, neoplastic melanocytes. "Previous studies on TLR8 mainly focused on breast cancer, melanoma, prostate cancer, and other models, and rarely involved bladder cancer." (PMID 38063246, 2023). "It has been proven that TLR8 signaling activation inhibits the immunosuppressive effect of melanoma and breast cancer-derived Treg cells." (PMID 37786827, 2023). "TLR8 signaling-mediated reprograming of glucose metabolism and function in human Tregs cells can enhance anti-tumor immunity in vivo in a melanoma adoptive transfer T cell therapy model." (PMID 34026764, 2021). "We studied the role of Toll-Like Receptor-8 (TLR8) engagement on peripheral CTLs activated with melanoma antigen MART-1-expressing artificial antigen-presenting cells (AAPCs)." (PMID 25866635, 2015). "Altogether, this phenotypic study suggests that TLR8 engagement on CTLs could lead to the obtention of functionally more relevant CTLs for melanoma immunotherapy, with a particular property to home to the skin." (PMID 25866635, 2015). "However, these TLR8-stimulated lymphocytes displayed increased cytotoxic activity against specific peptide-pulsed target cells related to an increase in specific anti-melanoma CTL functional avidity." (PMID 25866635, 2015). "NOD/SCID immunodeficient mice could be used to investigate TLR8 agonist-treated specific CTL effects on tumor regression after injection of human melanoma cells." (PMID 25866635, 2015). "We next determined whether we can enhance anti-tumor immunity by inhibiting tumor-specific T-cell senescence through TLR8 signaling in this adoptive transfer therapy melanoma model." (PMID 25231413, 2014). "Finally, we clearly showed in this study that TLR8 engagement increased melanoma peptide-specific CTL cytotoxicity and functional avidity in vitro, and that these CTLs could display a more suitable phenotype for immunotherapy." (PMID 25866635, 2015). "In this study, we found that HLJD significantly upregulated the expression of TLR7 and TLR8 and activated IFN-Is signaling in melanoma tissues, acting in part as a safe and cost-effective TLR agonist." (PMID 38605368, 2024). "The immune and inflammatory response node contained 99 proteins and genes directly involved in the immune response such as interleukins and chemokines; T lymphocyte markers such as CD96, TLR8, CD80; or CCR5, beta-2-microglobulin (B2M) or absent in melanoma 2 (AIM2)." (PMID 37686682, 2023).